STARD13 (StAR related lipid transfer domain containing 13)
Diseases named in the same sentence as STARD13 in open-access papers (continued):
Sharing a sentence is not in itself a finding about the gene and the disease.
ovarian carcinoma (2 papers, 2020 to 2022). A malignant neoplasm originating from the surface ovarian epithelium. "This was further confirmed by mining the Oncomine database for microarray analysis of StarD13 expression in different ovarian cancer types from two datasets." (PMID 34958986, 2022). "We therefore next tested the ability of StarD13 to modulate ovarian cancer cell matrix degradation using the gelatin invadopodia assay." (PMID 34958986, 2022). "In ovarian cancer cells, StarD13 depletion also led to an increase in cortactin-labeled and WASP-labeled potential invadopodia, while Cdc42 depletion completed abolished any of these structures." (PMID 34958986, 2022). "To understand the role of StarD13 in ovarian cancer cells, we determined the expression profile of StarD13 in normal ovarian tissues as well as in tissues obtained from patients with ovarian adenocarcinoma." (PMID 34958986, 2022). "Cdc42 is directly implicated in the regulation of cancer cell invasion, therefore we investigated the role of StarD13 in regulating the invasion of ovarian cancer cells." (PMID 34958986, 2022). "In this study, we investigate the potential role of the Cdc42 GAP StarD13 in the modulation of cell motility, invasion in ovarian cancer cells." (PMID 34958986, 2022). "This shows that the regulation of activation/inactivation cycling of RhoA is also needed in ovarian cancer cells for effective cell migration, however, this regulation seems to be StarD13-independent." (PMID 34958986, 2022). "This study provides an in-depth understanding of the role of StarD13 in ovarian cancer cells, as well as uncovers the key targets mediating StarD13 effects on cell proliferation, motility, invadopodia formation and invasion." (PMID 34958986, 2022). "This strongly suggests that StarD13 is a GAP for Cdc42 in ovarian cancer as it was shown in other tumor types." (PMID 34958986, 2022). "StarD13 expression levels were significantly lower in almost all ovarian cancer types investigated relative to the normal tissues, thus suggesting a potential tumor suppressor role for StarD13 in ovarian cancers." (PMID 34958986, 2022). "To further understand the mechanism of StarD13 regulation of ovarian cancer invasion, we investigated the effects of StarD13 and Cdc42 inhibition on invadopodia formation." (PMID 34958986, 2022). "Knock down of StarD13 however, showed an increase in GTP-Cdc42, strongly suggesting that StarD13 is a GAP for this Rho GTPase in ovarian cancer cells, similarly to findings in other tumor types." (PMID 34958986, 2022). "After having established the anti-proliferative potential of StarD13 in ovarian cancer cells, we investigated its ability to modulate cell motility using two approaches: wound healing and time-lapse assays." (PMID 34958986, 2022). "Both BRCA2 and STARD13 are well known tumor-suppressors, and upregulation of N4BP2L1 and N4BP2L2 has been associated with positive prognosis in ovarian cancer cases." (PMID 32404140, 2020). "In addition, a slight increase in the adhesive ability of ovarian cancer cells was observed after StarD13 depletion." (PMID 34958986, 2022). "Finally, the data show that RhoA is required for matrix degradation and invasion of ovarian cancer cells independently from StarD13." (PMID 34958986, 2022). "In addition to the effect on actin-rich protrusion, StarD13 silencing increased matrix degradation and ovarian cancer cell invasion." (PMID 34958986, 2022). "However, the expression of StarD13 in ovarian cancer tissues versus normal ovarian tissues as well as the role of StarD13 in ovarian cancer cell proliferation, motility and invasion remains unknown." (PMID 34958986, 2022). "The results obtained support the tumor suppressor role of StarD13 and that StarD13 is a GAP for Cdc42 in ovarian cancer cell lines, as was previously shown in other tumor types." (PMID 34958986, 2022). "This could be due to the lack of effect on RhoA activity in ovarian cancer cells depleted of StarD13." (PMID 34958986, 2022).
ovarian carcinoma (continued). "StarD13 depletion does not affect the 2D motility of ovarian cancer cells." (PMID 34958986, 2022). "DLC1 is not deleted in ovarian carcinoma tissues, albeit expressed at a lower level than normal ovarian tissues, which could compensate for the GAP activity of StarD13." (PMID 34958986, 2022).
brain arteriovenous malformations (1 paper, 2018). "The STARD13 locus has been reported to be associated with aneurysm and sporadic brain arteriovenous malformations." (PMID 30148849, 2018).
osteoporosis (1 paper, 2025). A condition of reduced bone mass, with decreased cortical thickness and a decrease in the number and size of the trabeculae of cancellous bone (but normal chemical composition), resulting in increased fracture incidence. "Some recent microRNA-based studies have shown that miR-125 is up-regulated in patients with osteoporosis, and STARD13 is the target of it." (PMID 40943102, 2025).
ovarian adenocarcinoma (1 paper, 2022). An adenocarcinoma that arises from the ovary. "Immunohistochemistry analysis showed a significant 2-fold decrease in the expression levels of StarD13 in ovarian adenocarcinoma biopsies as compared to normal ones." (PMID 34958986, 2022).
ovarian tumors (1 paper, 2022). "This could indicate that, while in other tumor types StarD13 is the main GAP for RhoA due to the absence of DLC1, in ovarian tumors DLC1 mainly drives this inhibition." (PMID 34958986, 2022).
prostate hyperplasia (1 paper, 2024). "To delve deeper into the potential mechanisms of DACH1, CACNA1D, STARD13, and RUNDC3B in regulating prostate hyperplasia, we stratified prostate hyperplasia samples according to the levels of expression of these genes and conducted GSEA." (PMID 39703506, 2024). "ROC curves were then used to assess the predictive potential of these key gene markers in prostate enlargement, revealing AUC values of 0.885, 0.874, 0.885, and 0.874 for DACH1, CACNA1D, STARD13 and RUNDC3B, respectively." (PMID 39703506, 2024).
rectal tumors (1 paper, 2014). "This was in accordance with previous studies where StarD13 was found to be underexpressed in several cancer types including lung, colon, gastric, ovarian, uterine, renal and rectal tumors." (PMID 24627003, 2014).
resistant hypertension (1 paper, 2021). "One SNP-SNP interaction model, rs3801888 (alpha: 0.028; SNX10) and rs2858808 (alpha: -1.39; STARD13), was identified by the dominant encoding for resistant hypertension." (PMID 34086673, 2021).
Stroke (1 paper, 2024). Sudden impairment of blood flow to a part of the brain due to occlusion or rupture of an artery to the brain. "On the protein level, microglia in the non-nodular (NA)WM rarely expressed FABP5, DAGLB, IAH1, or STARD13, and microglia nodules in MS compared to in stroke were more often FABP5+, DAGLB+, or STARD13+." (PMID 38396116, 2024). "The percentage of HLA+ cells that were also FABP5+, DAGLB+, STARD13 or IAH1+ was similar for MS and stroke (NA)WM." (PMID 38396116, 2024).
tumor (35 papers, 2011 to 2025). "Thus, the activity of STARD13-correlated ceRNA network has been linked to breast CSCs, i.e., tumor seeding." (PMID 29848346, 2018). "At the level of competitive RNA interactions, PUM2 functions as a tumor suppressor by competing with pro-oncogenic miRNAs miR-590-3p/miR-9 for binding at the 3’ UTR of STARD13 mRNA." (PMID 41019082, 2025). "That corroborated the potential tumor suppressive function of StarD13 since, once depleted, normal lung cells recapitulated the tumor phenotype and formed invasive structures." (PMID 34958986, 2022). "StarD13 inhibition of cell proliferation is also in line with a potential tumor suppressor function of this protein." (PMID 34958986, 2022). "LINC01089 served as a tumor-inhibitor in LUAD by targeting miR-301b-3p/STARD13 axis, providing an innovative insight into LUAD therapies." (PMID 34281560, 2021). "Among the most significantly downregulated targets were MAT2A and the tumor suppressive genes STARD13 and ZNF132." (PMID 34797887, 2021). "It is inversely correlated with STARD13, ZNF132 and MAT2A, which are implicated in tumor development." (PMID 34797887, 2021). "Lower Th1/Th2 cell ratio, higher DC cell infiltration, and higher Treg cell infiltration were observed in ARHGAP17, ARHGAP24, and ARHGAP37 (STARD13), indicating a tumor-promoting microenvironment." (PMID 34307347, 2021). "The same anti-cancer effect was observed in WI38 normal lung cells, where cell viability significantly increased (around 5 fold) in WI38 cells depleted of StarD13 as compared to the control, further suggesting the tumor suppressor role of StarD13 in lung." (PMID 32900380, 2020). "We have previously investigated the role of StarD13 in cancer cell motility and, revealed that despite its anti-metastatic functions the StarD13 tumor suppressor is required for cell migration." (PMID 32900380, 2020). "Overexpression of PUM2 can inhibit the tumor progression by competitively binding to the 3′UTR of STARD13 with miR‐590‐3p and miR‐925." (PMID 32997416, 2020). "Other groups have also reported low expression levels of StarD13 in in several tumor types, due to gene deletion or epigenetic modifications." (PMID 32900380, 2020). "This suggests a dual role of StarD13; as 1- a tumor suppressor which attenuates RhoA (hence Raf-1/MEK/ERK proliferation and survival pathway) as well as 2- an invasion suppressor, which inhibits Cdc42." (PMID 32900380, 2020). "It was proposed that STARD13 has tumor suppressor functions, which is supported by cell culture-based experiments but not by in vivo studies." (PMID 28783714, 2017). "We conclude that StarD13 tumor suppressor activity is contextual where tumor cells manage to exploit alternative mechanisms to escape inhibition." (PMID 24627003, 2014). "We observed that, while the level of StarD13 expression decreases in cancer tissues compared to normal tissues, it increases as the grade of the tumor increased." (PMID 24627003, 2014). "Then, its level of expression decreased in grades I and II; however, as we moved on to higher grades of the tumor, StarD13 showed a significant increase in its level of expression." (PMID 24627003, 2014). "Taken together, our data show that even though StarD13 is known to be a tumor suppressor, it is needed for motility." (PMID 24627003, 2014). "This was supplemented by data obtained from Oncomine database in which mRNA levels of StarD13 were reduced in grades I and II as compared to normal, however, were shown to increase in higher grades of the tumor." (PMID 24627003, 2014). "Their findings attempt to establish novel cooperation and coordination between oncogenic Rho GTPase/F-actin function and the tumor-suppressive LATS1/2 (Hippo pathway) as two synergistic components of the STARD13-correlated ceRNA in modulating breast CSC characteristics." (PMID 39170516, 2024).
tumor (continued). "Moreover, DLC1, a closely related protein to StarD13 and a well-established tumor suppressor, which inhibits proliferation and induces apoptosis, has also been shown to positively regulate cell migration." (PMID 32900380, 2020). "As a target of several miRNAs, StarD13 plays a critical role in regulating tumor progression." (PMID 30899277, 2019). "Notably, the tumor-seeding ability of STARD13-correlated ceRNAs-3′UTR-overexpressed cells was significantly decreased at a density of 1 × 105 and 1 × 104 cells." (PMID 29848346, 2018). "Although all cell lines could form tumors at a density of 1 × 106 cells, STARD13-correlated ceRNAs-3′UTR-overexpressed cells showed a decrease of tumor size and weight." (PMID 29848346, 2018). "Tang and collaborators studied the effects of miR-125 deregulation on metastasis formation, finding that miR-125b induces metastasis by targeting STARD13 mRNA in MCF-7 and MDA-MB-231 BC cells, in contrast with the tumor suppressive action described before." (PMID 38525735, 2024). "Steroidogenic acute regulatory protein-related lipid transfer domain-containing protein 13 (StarD13) is a GAP for RhoA and Cdc42 with potential tumor suppressor functions." (PMID 34958986, 2022). "StAR-related lipid transfer domain containing 13 (StarD13), a GAP for Rho GTPases, has been confirmed as a tumor suppressor." (PMID 30899277, 2019). "The data consistently showed that StarD13 mRNA levels are lower in tumors relative to non-tumor tissues, as is typically the case for tumor suppressors." (PMID 32900380, 2020). "In previous studies, we established the tumor suppressor StarD13 (steroidogenic acute regulatory protein)-related lipid transfer domain 13) as a GTPase-activating protein (GAP) that specifically inhibits RhoA and Cdc42 in GBM cells and other tumor models." (PMID 31698752, 2019). "CR has known anti-tumor activity in mammals, hence downregulation of the expression of a potential tumor suppressor gene is counterintuitive, however, Stard13 might have some other functions, which cannot be ruled out." (PMID 28783714, 2017). "The results showed that StarD13 is underexpressed in tumor tissues relative to non-tumor (grade 0)." (PMID 24627003, 2014). "In same regard, the lack of LATS1/2 reduced the inhibitory effects of the STARD13-correlated ceRNA network on EMT features of CSC, indicating that the tumor-suppressive effects of the STARD13-correlated ceRNA network are mediated by LATS1/2 modulation." (PMID 39170516, 2024). "In line with this, the absence of LATS1/2 attenuated the inhibitory roles of STARD13-correlated ceRNA network on CSC and EMT traits, highlighting that STARD13-correlated ceRNA network exerts its tumor-suppressive effects at least partly through regulating LATS1/2." (PMID 29848346, 2018). "Moreover, RNA-seq data from each of 40 advanced PDAC tumor specimens from the TCGA data base indicate a negative correlation between expression of miRNA-125b and five of six potential target genes (BAP1, BBC3, NEU1, BCL2, STARD13)." (PMID 25184537, 2014).
cancer (27 papers, 2009 to 2025). A tumor composed of atypical neoplastic, often pleomorphic cells that invade other tissues. "Normal lung cells depleted of StarD13 also produced invadopodia, otherwise a unique hallmark of invasive cancer cells." (PMID 32900380, 2020). "Knowing that Cdc42 is the main effector of StarD13 in these cells, we then looked at the effect of StarD13 depletion on cell protrusion, a main event during cancer migration regulated by Cdc42." (PMID 34958986, 2022). "STARD13 reportedly functions in cytoskeletal reorganization, proliferation, and motility, all of which are processes necessary for cancer progression." (PMID 34797887, 2021). "Mechanistically, StarD13 effects on cancer cell motility and adhesion in vitro were mediated by its RhoA GAP activity on RhoA and its indirect Rac1 regulation." (PMID 32900380, 2020). "The deleted in liver cancer 1 (DLC-1 or STARD12), DLC-2 (STARD13), and DLC-3 (STARD8) RhoGAPs are frequently down-regulated in cancer and associated with poor prognosis." (PMID 33142932, 2020). "Our findings are contradictory to reported by other groups where StarD13 was found to negatively regulate the motility of cancer cells." (PMID 32900380, 2020). "The differential role of StarD13 in the two modes of migration (2D motility versus 3D invasion) is only indicative of cancer cells relying on different pathways for different modes of migration." (PMID 32900380, 2020). "To determine the anticancer potential of StarD13, we used the WST-1 assay and compared the viability of control and StarD13 depleted A549 cancer cells." (PMID 32900380, 2020). "In summary, our study provided new insights into the function of miR-125b during the metastasis of breat cancer cells and also suggested the role of miR-125b in pro-metastasis by targeting STARD13." (PMID 22693547, 2012). "Indeed, several studies have shown that StarD13 is under expressed in many types of tumors, and that the overexpression of StarD3 inhibits cancer cell growth and proliferation." (PMID 34958986, 2022). "However, Cdc42 depletion was able to reverse the effect of StarD13 depletion in SKOV-3 and Caov-3 cancer cells and reduce the number of invaded cells by around 50% as compared to the StarD13 depleted cells." (PMID 34958986, 2022). "In addition, here we demonstrate a key inhibitory role for StarD13 in the regulation of cellular proliferation in normal and cancer lung cells." (PMID 32900380, 2020). "The effect on cellular proliferation, viability and cell cycle progression upon manipulating the level of StarD13 expression was then studied in addition to investigating its RhoGAP activity in cancer cell motility as well as its effect on cellular invasion in vitro." (PMID 24627003, 2014). "At stage 3, STARD13, CBFA2T3, RECK, and SASH1 had strong accordant/discordant effects on expression of genes in cancer, while APC, EXT1, NBL, KLK10, and PTCH1 had very weak accordant/discordant impacts on expression of genes in cancer." (PMID 33580150, 2021). "These suggest that RAP1A, STARD13, SASH1, RECK, and CBFA2T3 had big positive network effects on down-expression of genes in stage-3 cancer." (PMID 33580150, 2021). "To confirm the GAP function of StarD13, we performed a pull-down assay to investigate the differences in GTP loading of RhoA and Cdc42 in SKOV-3 and Caov-3 cancer cells in the presence or absence of StarD13." (PMID 34958986, 2022). "Hence, the strong TS genes SASH1, STARD13, RECK, CBFA2T3, RASSF2, RAP1A, and ARHGEF12 can be used as specific biomarkers for diagnosis of NSCLC cancer." (PMID 33580150, 2021).
infection (3 papers, 2012 to 2024). The state of being infected such as from the introduction of a foreign agent such as serum, vaccine, antigenic substance or organism. "EMT marker (see in main text) expressions were measured in MDA-MB-231 cells with STARD13- or its ceRNAs-3′UTR overexpression plus LATS1 or LATS2 or LATS1/2 knockdown by lentiviral infection." (PMID 29848346, 2018). "(A) Lentiviral infection efficiency of MDA-MB-231 cells stably expressing STARD13-3′UTR, CDH5-3′UTR, HOXD1-3′UTR, and HOXD10-3′UTR was examined by qRT-PCR." (PMID 29848346, 2018). "LATS1/2 was knocked down in MDA-MB-231 cells with STARD13-correlated ceRNAs-3′UTR overexpressing by lentivirus shRNAs infection." (PMID 29848346, 2018). "(B) Lentiviral infection efficiency of MCF-7 cells stably depleted of STARD13, CDH5, HOXD1, and HOXD10 was verified by Western blot analysis." (PMID 29848346, 2018).
adenocarcinoma (2 papers, 2009 to 2020). A common cancer characterized by the presence of malignant glandular cells. "Similarly, this study uncovered that StarD13 expression levels in human NSCLC adenocarcinoma tissues are low as compared to its expression levels in tissues from normal biopsies." (PMID 32900380, 2020).
STARD13 also shares sentences with these, for which no sentence is quoted: colon cancer (3 papers); X-linked intellectual disability (3); cardiovascular disease (2); cervical carcinoma (2); melanoma (2); Anxiety (1); anxiety disorder (1); bladder cancer (1); brain disorder (1); breast tumors (1); celiac disease (1); colitis (1); focal segmental glomerulosclerosis (1); follicular lymphoma (1); Hypertension (1); inflammatory bowel disease (1); Insulin resistance (1); mental retardation (1); metabolic disorders (1); metastatic tumors (1); multiple sclerosis (1); non-small cell lung adenocarcinoma (1); Obesity (1); psoriasis (1); ventricular septal defect (1).